NLRP3 (NLR family pyrin domain containing 3)
Diseases named in the same sentence as NLRP3 in open-access papers (continued):
Sharing a sentence is not in itself a finding about the gene and the disease.
myocardial infarction (continued). "To further explore whether GDF11 plays an important role in adjusting cardiomyocytes pyroptosis in myocardial infarction, we evaluated the protein levels of NLRP3, ASC, cleaved-caspase-l (c-caspase-1), and GSDMD-N in ischemic heart and hypoxia cardiomyocytes with or without GDF11 treatment." (PMID 33100331, 2020). "Literature reports that pretreatment with the NLRP3 inhibitor INF195 can significantly inhibit IL-1β production, thereby reducing inflammation and significantly decreasing the myocardial infarction area." (PMID 40486827, 2025). "In the context of myocardial infarction or myocardial I/R injury, DAMPs such as HMGB1, HSPs, mtDNA, and ATP promote cellular focal death by activating the NLRP3 inflammasome, caspase-1, caspase-4/5/11, and GSDMD." (PMID 40877572, 2025). "In MI/R injury, HSYA suppressed the NLRP3 inflammasome by modulating the AMPK/mTOR signaling pathway, thereby reducing myocardial infarct size and decreasing cardiomyocyte apoptosis, ultimately improving heart function." (PMID 39925805, 2025). "Betulin attenuated the cardiac inflammatory response, decreased myocardial infarct size, and enhanced cardiac electrical signaling by modulating the SIRT1/NLRP3/NF-κB signaling pathway." (PMID 39925805, 2025). "During acute myocardial infarction (AMI), dying heart myocytes initiate the assembly of the NLRP3 inflammasome by activating P2X7R via ATP release." (PMID 39925805, 2025). "In myocardial infarction inflammation, CXCR4 upregulation activates the nuclear translocation and phosphorylation of NF-κB, thus promoting NLRP3 inflammasome activation." (PMID 39684834, 2024). "It inhibits the activation of the NLRP3 inflammasome, exhibiting antidepressant and neuroprotective effects, and significantly reduces MMP-9 expression in myocardial infarction models." (PMID 39295943, 2024). "Salvianolate treats myocardial infarction by inhibiting the TGF-β1/Smad2/3 and TXNIP/NLRP3 inflammasome signaling pathways." (PMID 36909150, 2023). "Colchicine, which inhibits tubulin polymerization and the assembly of the multimeric NLRP3 inflammasome, reduces major cardiovascular events (MACE) in patients with chronic stable coronary artery disease as well as those with recent myocardial infarction." (PMID 37092016, 2023). "In humans, previous studies have shown increased expression of NLRP3 inflammasome, IL-1β, and IL-18 in patients with CAD, particularly in those with acute myocardial infarction compared with those with stable angina." (PMID 36674682, 2023). "ACS: acute coronary syndrome, CVD: cardiovascular disease, HF: heart failure, ECM: extracellular matrix, IL: interleukin, NLRP3: nucleotide-binding domain, leucine-rich-containing family, pyrin domain-containing-3, MI: myocardial infarction, SICM: sepsis-induced cardiomyopathy." (PMID 37637634, 2023). "As a result, linagliptin improved cardiac contractility, suppressed mRNAs expression of NLRP3, ASC, IL-1β, collagen I, and collagen III in the border zone of myocardial infarction, and prevented cardiac hypertrophy both in wild-type (WT) and db/db mice." (PMID 36320147, 2022). "In recent years, the NLRP3 inflammasome has been shown to contribute to the development of many cardiovascular diseases, including diabetic cardiomyopathy, myocardial infarction, and MI/R injury, as well as myocarditis." (PMID 35997820, 2022). "Conversely, inhibiting the production of NLRP3 inflammasome or GSDMD induced pyroptosis can reduce MIRI and myocardial infarction size." (PMID 35571159, 2022). "In secondary prevention of cardiovascular events in patients with previous acute myocardial infarction (AMI), blockage of IL-1β performed within the CANTOS trial suggested the potential of NLRP3 as a target for AMI therapies." (PMID 35558073, 2022). "Therefore, the NLRP3 inflammasome might serve as a promising therapeutic target providing new mechanisms for understanding the effect of artemisinin during the evolution of myocardial infarction." (PMID 34443594, 2021).
myocardial infarction (continued). "To search the potential mechanism of biological effect of H2 on myocardial infarction, we had set MCC950, the selective NLRP3 inflammasome inhibitor, as a positive control group." (PMID 34402164, 2021). "Using Wistar rats, we investigated whether Calhex231 ameliorates myocardial fibrosis through the autophagy‐NLRP3 inflammasome pathway in macrophages post myocardial infarction (MI)." (PMID 33043596, 2020). "Intriguingly, diabetes was demonstrated to further deteriorate cardiac functions and augment HF after myocardial infarction by enhancing the activation of AIM2 and NLRC4 inflammasome instead of NLRP3 inflammasome." (PMID 32508013, 2020). "Interestingly, the extent of injury after fulminant hepatitis or myocardial infarction is time-of-day dependent under the control of the clock, and chronotherapy represents a promising approach for the management of pathologies involving deregulation of NLRP3 signaling." (PMID 32849554, 2020). "In an acute myocardial infarction (AMI) trial, P2X7 was revealed to be effective at activating NLRP3, triggering an inflammatory response which negatively impacts prognosis." (PMID 31354731, 2019). "Multiple reports have investigated the pathological role of the NLRP3 inflammasome after myocardial infarction or I/R injury using ASC, caspase-1, or NLRP3 null mice." (PMID 29511093, 2018). "For instance, NLRP3 inflammasome knockout in endothelial progenitor cells (EPCs) was reported to rescue angiogenesis in diabetic mice with myocardial infarction, suggesting that the PI3K/AKT/mTOR cascade acts as a downstream effector of NLRP3-mediated inflammatory responses." (PMID 40313483, 2025). "Additionally, the size of myocardial infarction, which was reduced in the SEV group, increased with NLRP3 activation compared to the SEV group." (PMID 40901632, 2025). "The MRC-ILA-Heart study, which included 182 patients experiencing small acute myocardial infarction (AMI), revealed that NLRP3 inflammasome activation and the heightened IL-1 activity during the acute phase of myocardial infarction correlated with escalating heart failure risk." (PMID 38650918, 2024). "The myocardial infarction area was significantly reduced in rats with myocardial infarction injected with KLF3-AS1 exosome, and the expressions of NLRP3, caspase-1, GSDMD, IL-1β and IL-18 in KLF3-AS1-overexpressed myocardial infarction mice were also significantly decreased." (PMID 37396588, 2023). "GXDSF can reduce the myocardial infarction area and alleviate the damage to myocardial structure in rats with MIRI, which may be related to the regulation of the NLRP3." (PMID 37098925, 2023). "After myocardial infarction, ASC speck formation was observed in mouse cardiac ECs, suggesting that endothelial NLRP3 inflammasomes may play a role in MI." (PMID 35600331, 2022). "In the current study we do not provide evidence that NLRP3-inflammasome inhibition is beneficial in the acute setting after myocardial infarction." (PMID 36551811, 2022). "In experimental models, NLRP3 (NOD-like receptor family, pyrin domain-containing 3) inflammasome-targeted strategies might be beneficial in acute myocardial infarction." (PMID 34884196, 2021). "Moreover, investigations within a porcine myocardial infarction model have shown that MCC950 notably diminishes infarct size and alleviates cardiomyocyte pyroptosis through the inhibition of NLRP3 inflammasome activation, consequently reducing the release of inflammatory factors (IL—1β, IL—18)." (PMID 40877572, 2025). "In fact, a relationship between GSDMD and granulopoiesis has been reported in myocardial infarction (MI), albeit in the opposite direction, with GSDMD promoting granulopoiesis through the NLRP3-GSDMD-IL-1β signaling pathway." (PMID 38831451, 2024). "NLRP3 inflammasome is a proven predictor of adverse outcomes in cardiovascular disease, but its specificity in stratifying inflammatory activity in patients with myocardial infarction (MI) has not been demonstrated." (PMID 39590595, 2024).
myocardial infarction (continued). "In addition, there are studies showing that the absence of NLRP3 results in increased myocardial infarct size after in vivo ischemia–reperfusion." (PMID 39590595, 2024). "Furthermore, EA reduced the infarct area and increased the ejection fraction (EF) by inhibiting the expression of NLR family pyrin domain containing 3 (NLRP3) and AMP-activated protein kinase (AMPK)-dependent autophagy in an animal study of an acute myocardial infarction rat model." (PMID 36639647, 2023). "NLRP3 inflammasome-activated NLRP3/ASC-dependent inflammatory responses result in the release of significant amounts of caspase-1 and IL-1β, and these innate immune responses play an important role in diabetic cardiomyopathy, myocardial infarction, and MI/R injury." (PMID 29062465, 2017). "Similarly, studies using the NLRP-3 inflammasome inhibitor, MCC950, resulted in slowing the development of HF in both models of myocardial infarction (MI) and pressure overload by suppressing IL-1β release." (PMID 32604981, 2020). "The myocardial infarct size, CK-MB and LDH release in diabetic rats were significantly higher than those in non-diabetic rats, accompanied by increased NLRP3 activation and pyroptosis." (PMID 36873396, 2023). "The myocardial infarct size, CK-MB, and LDH release in the diabetic rats subjected to MI/R were significantly higher than those in the nondiabetic rats, accompanied with increased NLRP3 inflammasome activation and increased pyroptosis." (PMID 29062465, 2017).
diabetic nephropathy (216 papers, 2012 to 2026). "further showed that NLRP3 activation in glomerular intrinsic cells (particularly podocytes) exacerbates glomerular injury in murine models of diabetic nephropathy, highlighting a conserved pathogenic role across glomerulopathies." (PMID 41357229, 2025). "Endoplasmic reticulum stress and chronic sterile inflammation have been implicated in the pathogenesis of diabetic nephropathy, and intriguingly, (+)-catechin has been reported to regulate endoplasmic reticulum stress and NLRP3-associated inflammation." (PMID 41020857, 2025). "Podocyte injury in murine models of diabetic nephropathy is associated with NLRP3-induced inflammation and pyroptosis." (PMID 40864768, 2025). "On the other hand, the inflammatory processes involving NFKB and NLRP3 pathways have also been associated with the inhibition of renal mitochondrial biogenesis by SIRT/PGC-1α/NRFs in diabetic nephropathy and CKD transition." (PMID 41154550, 2025). "A number of renal diseases, including acute renal failure, chronic renal failure, diabetic nephropathy, and crystal-related nephropathy have been linked to the NLRP3 inflammasome." (PMID 38114914, 2023). "In diabetic nephropathy, NLRP3 inflammasome activation has been reported and NLRP3 or caspase-1 deficiency improved albuminuria and the fractional mesangial area in diabetic mice." (PMID 37371050, 2023). "Persistent or dysregulated activation of the NLRP3 inflammasome has been implicated in the development of glomerulonephritis, diabetic nephropathy, tubulointerstitial nephritis, and other inflammatory renal disorders." (PMID 37371054, 2023). "Treatment options for diabetic nephropathy are limited, and research that examines the impact of directly targeting the NLRP3 inflammasome, or associated downstream components are beginning to gain favour, with several agents currently in clinical trials." (PMID 35755447, 2022). "Of significance, inflammatory mediators produced by the NLRP3 inflammasome are implicated in diabetic nephropathy (DN)." (PMID 29515457, 2018). "DN can be considered an inflammatory disease and several reports have demonstrated that NLRP3 inflammasome activation is associated with diabetic nephropathy." (PMID 27706238, 2016). "Diagram illustrating conditions associated with NLRP3 inflammasome activation, including acute kidney injury, diabetic nephropathy, chronic kidney disease, urinary tract infection, lupus nephritis, polycystic kidney, kidney cancer, hydronephrosis, kidney stones, and renal fibrosis." (PMID 41357229, 2025). "Furthermore, studies have demonstrated that the activation of the mitochondrial ROS‐TXNIP/NLRP3 axis underlies renal tubule injury observed in patients with diabetic nephropathy." (PMID 40959205, 2025). "Additionally, mesangial cells have been proven to respond to high glucose-treated macrophage-derived exosomes by promoting the activation of the NLRP3 inflammasome and autophagy deficiency, thereby contributing to the development of diabetic nephropathy." (PMID 40519516, 2025). "Additionally, the purinergic receptor P2X7R has been implicated in mediating renal inflammation and injury in diabetic nephropathy through NLRP3 inflammasome activation." (PMID 38995008, 2024). "Finally, Ying and co-workers have recently observed that the binding of RAC1 to the pyrin domain containing 3 (NLRP3) activates the NLRP3 inflammasome in the kidney and accelerates the pathological processes underlying diabetic nephropathy." (PMID 36979960, 2023). "In the kidney, NLRP3 activation was associated with the progression of diabetic kidney disease." (PMID 37242177, 2023).
diabetic nephropathy (continued). "The NLRP3 inflammasome is a multiprotein complex involved in the processing and secretion of pro-inflammatory cytokines, and its activation has been implicated in the development of diabetic kidney disease." (PMID 37371054, 2023). "Targeting NLRP3 significantly reduces physical, biochemical, and molecular markers associated with diabetic nephropathy, providing protection from high glucose-induced glomerular injury, changes which initiate progression of kidney injury in both T1DM and T2DM." (PMID 35755447, 2022). "In an STZ-induced rat model of diabetic nephropathy (DN) with hyperuricemia and dyslipidemia, overexpression of NLRP3 inflammasome components [apoptosis-associated speck-like protein (ASC) and caspase-1] has been found to be associated with elevated IL-1β and IL-18 levels." (PMID 34267672, 2021). "In addition, NLRP3 was associated with renal function and inhibition of NLRP3 inflammasome activation prevents renal inflammation and fibrosis at least in part via suppression of oxidative stress in diabetic nephropathy." (PMID 32316547, 2020). "All these results suggest that the NLRP3 inflammasome may be an important pathogenic factor for the development of diabetic nephropathy, which is probably a new target for treatment of DN complications in the kidney." (PMID 31737627, 2019). "In diabetic nephropathy, NLRP3 inflammasome activation could cause lipid accumulation in podocytes." (PMID 40135589, 2025). "Previous studies have demonstrated that TMD1 alleviates inflammation via the NLRP3 pathway in diabetic nephropathy." (PMID 41503166, 2026). "Differently, astragaloside IV protects podocytes from diabetic nephropathy by modulating the NLRP3 inflammasome, a mechanism that parallels the action of ginsenosides Rg1, Rg2, and Rg5." (PMID 41415561, 2025). "Activation of the NLRP3 inflammasome contributes to diabetic nephropathy’s development, while inhibition of the NLRP3 inflammasome alleviates vascular calcification in diabetic nephropathy." (PMID 40864768, 2025). "Conversely, DIO intervention markedly diminished the heightened expression of NLRP3 inflammasome elements in diabetic nephropathy, suggesting its robust anti-inflammatory effect by curbing NLRP3 inflammasome activation in living organisms." (PMID 40458807, 2025). "In diabetic nephropathy mice, significant expression of NLRP3 and caspase-1 is observed in glomerular endothelial cells and podocytes." (PMID 41357229, 2025). "NLRP3 mRNA levels are elevated in the kidneys of patients with type 2 diabetes and are even higher in those with diabetic nephropathy (DN)." (PMID 41357229, 2025). "In a rat model of diabetic nephropathy, red ginseng berry decreased kidney tissue fibrosis by suppressing NLRP3 inflammasomes." (PMID 40841164, 2025). "Specifically, chronic low-grade inflammation, which is primarily mediated through the IL-6 and NLRP3 inflammasome signaling pathways, contributes to the pathogenesis of diabetic kidney disease." (PMID 41357229, 2025). "Studies have demonstrated that mitochondrial ROS‐TXNIP/NLRP3 axis activation contributes to tubular injury in diabetic nephropathy patients." (PMID 40959205, 2025). "It was reported that TMAO promoted diabetic kidney disease by activating NLRP3 inflammasome to induce pyroptosis." (PMID 40886370, 2025). "Hyperglycemia can promote the activation of TLR4, NF-κB pathway and NLRP3, and the subsequent inflammatory and fibrosis reactions, resulting in the emergence of diabetic nephropathy." (PMID 40176887, 2025). "Another major metabolite, CK, prevents HFD/STZ-induced diabetic nephropathy and high glucose-mediated mesangial cell damage by inhibiting NLRP3 inflammasome activation and the NF-κB/p38 pathway." (PMID 41415561, 2025).